STAT4 (signal transducer and activator of transcription 4)
Diseases named in the same sentence as STAT4 in open-access papers (continued):
Sharing a sentence is not in itself a finding about the gene and the disease.
tumor (continued). "Finally, Arg1, involved in the immunosuppressive function of MDSC, was found to be highly elevated in the draining lymph nodes of tumor bearing metastatic and non-metastatic Stat4−/− mice compared to tumor bearing WT counterparts." (PMID 32010142, 2019). "Taken together, our results indicate that enhanced expression of T cell immunosuppressive biomarkers resulting in a diminished anti-tumor T-cell immune response in the absence of STAT4 potentially contributes to the increased HNSCC tumor metastasis observed in in Stat4−/− mice." (PMID 32010142, 2019). "The results showed that STAT4 overexpression significantly decreased lactate levels in both OCI-LY19 cell and SU-DHL-2C cells, suggesting that STAT4 may play a key role in the relationship between lactate levels in the tumor microenvironment and the development of DLBCL." (PMID 37790933, 2023). "Interestingly, IL-17 gene expression in the tumors, draining lymph nodes and spleens were similar between WT and Stat4−/− tumor bearing mice, which may be due to IL-17 production by non-Th17 cells." (PMID 32010142, 2019). "Mechanistically, the authors demonstrated that STAT4 induced epithelial-mesenchymal transition (EMT) through cancer–stroma interactions, as STAT4 overexpression induced EMT of tumor cells in vivo but failed to induce EMT in vitro." (PMID 37173951, 2023). "The expression levels of STAT4, ETS1, or ESR1 did not significantly differ between the tumor and control groups." (PMID 35155179, 2021). "Diminished TNF-α production is suggestive of decreased anti-tumor activity in T cells, although T-cell TNF-α production does not appear to be mediated by STAT4 in our experimental HNSCC model." (PMID 32010142, 2019). "Based on the analysis of the literature, it can be stated that there are no studies analyzing the influence of STAT4 rs10181656, rs7574865, rs7601754, and rs10168266 SNVs on the development of LSCC, stages of the disease, spread to neck lymph nodes, and tumor differentiation and size." (PMID 39337665, 2024).
cancer (66 papers, 2012 to 2025). A tumor composed of atypical neoplastic, often pleomorphic cells that invade other tissues. "The genes BLK, CDC247, CSK, IRF5, STAT1, STAT4, and TNIP1 are associated with AIDs, and CDC37, DDX6, HSPA6, MAPT, PPIB, STAT1, and STAT4 are associated with cancers." (PMID 40429780, 2025). "The association of selected STAT4 genetic variants with only a few cancers has been described in the literature." (PMID 39337665, 2024). "Overexpression of STAT4 can be associated with either better or worse outcomes in cancers, depending on the type of cancer." (PMID 38611065, 2024). "In epithelial ovarian cancer, activated STAT4 is overexpressed and promotes cancer metastasis via tumor-derived Wnt7a-induced activation of cancer-associated fibroblasts." (PMID 38611065, 2024). "Specifically, the G allele of rs7574865 has emerged as a risk factor for cancer development and progression, and STAT4 levels in serum and peritumoral tissue of HCC patients with the GG genotype are significantly higher than those found in TT or TG carriers." (PMID 39575235, 2024). "Associations between STAT4 SNPs and cancer susceptibility have been reported in different cancer types, but the results have been inconsistent." (PMID 39575235, 2024). "When analyzing the LSCC clinical manifestations, we found that the STAT4 rs7601754 G allele was statistically significantly less common in the LSCC patients with T2-sized carcinoma than in the control group (p = 0.003)." (PMID 39337665, 2024). "STAT4 is the main IL-12 message-transducer molecule of the IL-12 pathway, and STAT4 gene variants have been implicated with an increased risk of several cancers, including stomach, colon, lung and breast." (PMID 32973967, 2020). "Interestingly, chemotherapy drugs promote the ubiquitination and proteasomal degradation of STAT4, and STAT4 has been associated with favourable prognoses in several cancer types." (PMID 40868162, 2025). "The positive association of STAT4 found in all 18 cancer types we analyzed suggests that this mechanism might play a major role in anticancer immunity and, possibly, response to ICB pan-cancer." (PMID 34430923, 2021). "Also, STAT4 phosphorylation underlies cell survival and proliferation in other cancer types." (PMID 41301480, 2025). "Moreover, they mentioned that 95.83% of the cancer tissue samples with metastases in the lymph nodes were positive for the expression of STAT4; they also mentioned an association between the expression of STAT4 with tumorigenesis and the severity of cervical lesions." (PMID 33076315, 2020). "The genes BLK, FAM167A, STAT1, STAT4, TNPO3, and TNIP1 are associated with AIDs, and CDC37, DDX6, MAPT, STAT1, STAT4, and UBE3A are associated with cancers." (PMID 40429780, 2025). "While only a few studies associate STAT4 SNPs with tumorigenesis, researchers have demonstrated that STAT4 expression is related to cancer." (PMID 39597056, 2024). "Although STAT4's role in immunity is well characterized, its involvement in cancer pathophysiology, especially in orchestrating chemoresistance, remains an area that needs to be investigated." (PMID 38429845, 2024). "STAT 4 plays a role in inducing inflammation as well as the differentiation of T helper 1 cells; however, little is known about STAT4’s role in cancer." (PMID 37173951, 2023). "Currently, based on our literature search, there are no selective inhibitors for STAT2 or STAT4, and yet STAT2 and STAT4 enhance cancer progression by promoting EMT." (PMID 37173951, 2023). "Historically, there are limited numbers of reports relating STAT2 and STAT4 dysregulation with the clinical characteristics and prognosis of human cancer." (PMID 36176415, 2022). "On the other hand, Ad‐loaded NK cells showed a higher immunotoxic effect than unloaded cells, providing a powerful supplement to Ad‐mediated cancer cell killing, owing to the activation of the STAT4‐granzyme B‐dependent pathways." (PMID 34747156, 2022).
cancer (continued). "We also found that tumors expressed higher STAT4 levels than adjacent tissues in the Office of Cancer Clinical Proteomics Research (CPTAC) database and through immunohistochemistry staining." (PMID 36348434, 2022). "After sorting out the current research data, it is found that STAT4 exists in different types of cancer and is a prognostic factor, which is consistent with the results obtained before." (PMID 34675977, 2021). "Signal transducer and transcription activator (STAT4) play an important role in development, proliferation, and immune defense, but overexpression can lead to several cancers." (PMID 33952249, 2021). "In A549 cells and cancer tissues #3 and #4, STAT4 expression was higher in the tissues that also had a high expression of CFH." (PMID 30987235, 2019). "Of the canonical pathways, the regulators of metabolism were most affected whilst MYC and STAT4 were predicted upstream regulators to be activated, as was the pathway modulating the anti-cancer pharmaceutical agent Streptozocin." (PMID 26987907, 2016). "In general, samples from R groups showed more enriched pathways related to inflammasomes, interferon gamma signaling, cancer immunotherapy by PD-1 blockade, T cell receptor and co-stimulatory signaling, IL-12 signaling mediated by STAT4, and co-stimulation by the CD28 family." (PMID 40593467, 2025). "The role of MAPK10 and STAT4 in cancer cell necroptosis has been unidentified." (PMID 37095524, 2023). "Like STAT2 and STAT4, the role of STAT6 remains largely unknown, though there is some evidence that STAT6 is associated with supporting the cancer stem cell niche in OvCa." (PMID 37173951, 2023). "Overexpression or agonist of STAT4 may be employed to induction favorable TME for cancer immunotherapy." (PMID 38107057, 2023). "Moreover, due to the deficiency in our understanding of STAT1, STAT2, STAT4, and STAT6 in cancer, selective inhibitors also remain elusive." (PMID 37173951, 2023). "Three kinds of extracts from herbs, namely, Pinellia pedatisecta Schott extract (PE), aqueous extract of Fritillariae cirrhosae (FC-AE), and Euphorbia helioscopia L. aqueous extract (EAE) exhibited their excellent performance in alleviation of COPD and anti-cancer through inhibiting STAT4 signaling." (PMID 36324680, 2022). "Previous studies show that high expression levels of the STAT4 protein may play distinct roles in different cancers." (PMID 35433680, 2022). "STAT2 and STAT4 remain nearly unresearched in PCa but could potentially be of interest as studies in other malignancies showed their involvement in cancer progression as well as suppression." (PMID 34638338, 2021). "For example, it is known that STAT4/STAT1 can form heterodimers in response to IL-35, an immunosuppressive cytokine associated with the generation of Tregs and with poor prognosis in some types of cancer." (PMID 33076315, 2020). "More researches need to be carried out to understand whether STAT4 affects anti-cancer immune responses and immunologic microenvironment in tumors." (PMID 32226303, 2020). "In addition, in the paired tissues where STAT4 expression levels were similar between normal and cancer cell lines, the CFH levels were also similar (tissue #1)." (PMID 30987235, 2019). "Given the previously established link between granulocytic CD11b+Ly6GhiLy6Cint MDSC expansion and cancer metastasis, our studies suggest a role for STAT4 in inhibiting immunosuppressive myeloid cell differentiation to prevent HNSCC establishment at lymph node metastatic sites." (PMID 32010142, 2019). "Additionally, we showed that SOX2-OT inverted the transcriptional association of STAT4 to CD4, which plays a key role in cancers." (PMID 26943771, 2016). "However, with the development of the disease, the expression of signal transducer and activator of transcription 4 (STAT4) is usually lost, leading to the switch from Th1 to Th2, causing cancer progression and immunosuppression, which is associated with worse clinical prognosis." (PMID 39758935, 2025).
cancer (continued). "However, in other forms of cancer STAT4 appears to play a protective role." (PMID 36548135, 2022). "The Ras association domain family 1 isoform A (RASSF1A), CTLA-4, and signal transducer and activator of transcription 4 (STAT4) genes are involved in the regulation of the cell cycle, apoptosis, and the autoimmune response against cancer." (PMID 41303553, 2025). "A pivotal aspect of our research was the elucidation of the IL-11/JAK1/STAT4/CBP signaling axis and its role in the upregulation of c-MYC, marking a significant progression in cancer biology." (PMID 38429845, 2024). "More importantly, it is clear that other STAT family members—STAT1, STAT2, STAT4, and STAT6—also contribute critical roles to cancer progression, either modulating the cancer cell directly or by altering cells of the TME." (PMID 37173951, 2023). "TFs associated with PIK3CA mutations were involved in WNT signaling, epithelial–mesenchymal transition, and cancer stem cell transition, including ELF3, TFEC, STAT4, STAT5B, NFATC1, GLIS1, CDC5L and AR." (PMID 36243974, 2022). "The gene of STAT genes was altered in 1,003 (9%) samples; STAT1, STAT2, STAT3, STAT4, STAT5A, STAT5B, andSTAT6 were altered in 2.3%, 1.7%, 2.0%, 2.4%, 1.6%, 1.9%, and 1.9% of the demanded pan-cancer samples." (PMID 36176415, 2022). "Our results showed STAT1 levels were higher in cancer tissues #3 and #4S, while STAT3 levels were higher in cancer tissues #3, #4, and #5, but the correlation with CFH expression was weaker than that of STAT4." (PMID 30987235, 2019). "STAT4 is a member of the Signal Transduction and Transcription Activating Factor (STAT) gene family and can participate in various pathways that affect the occurrence and progression of cancer." (PMID 41284376, 2025). "The influence of STAT4 rs10181656, which is in the third intron, on cancer has not yet been analyzed in the literature." (PMID 39337665, 2024). "Cytotoxic T-lymphocyte-associated protein 4 (CTLA4), Ras association domain-containing protein 1 isoform A (RASSF1A), and signal transducer and activator of transcription 4 (STAT4) genes regulate the cell cycle, apoptosis, and the autoimmune response against cancer." (PMID 37893134, 2023). "In addition, the distribution of STAT1, STAT2, STAT3, STAT4, STAT5A, STAT5B, and STAT6 expression in CD8+ T cells in pan-cancer were displayed, which presented that STAT1 and STAT2 had prominent up-regulation in CD8+ T cell with ISG IFIT1." (PMID 36968603, 2023). "Crytotanshinone (CPT) showed potential therapeutic value in animal breast model through enhancing cytotoxic CD4+ T cells by up-regulating JAK2 and STAT4 phosphorylation, suggesting that STAT4 may be play opposite function with STAT3 in human cancers." (PMID 28422733, 2017). "Furthermore, an up-regulated inflammatory gene analysis identified the involvement of transcription factors, such as STAT4, EGR1, and FOSL1, which regulate cancer as well as inflammation in aging processes." (PMID 27153548, 2016). "Implied by these findings, the STAT4 gene may induce STAT4+T cell infiltration through TNFSF12‐TNFRSF12A and TNF‐TNFRSF1A, further activating PANoptosis in epithelial cells and inhibiting cancer progression." (PMID 41284376, 2025). "Additionally, the distribution of STAT1, STAT2, STAT3, STAT4, STAT5A, STAT5B, and STAT6 expression in CD4+ T cells in pan-cancer were also clearly illustrated, which showed that STAT1 and STAT2 expression were notably up-regulated in CD4+ Treg cell with marker OSA1 and CD4+ T cell with ISG IFIT1." (PMID 36968603, 2023).
cancer (continued). "For the nine added TF genes, seven of them were reported to take part in apoptosis in various types of cancer or diseases; these seven TFs are STAT3, ETS1, LEF1, STAT4, E2F3, ATF3, and HMGA2, which have not been annotated by GO yet." (PMID 22952919, 2012).
infection (48 papers, 2008 to 2025). The state of being infected such as from the introduction of a foreign agent such as serum, vaccine, antigenic substance or organism. "STAT4-deficient mice are susceptible to infection with intracellular pathogens, have decreased delayed-type hypersensitivity (DTH) responses, and have attenuated T cell responses." (PMID 34138758, 2021). "In contrast to the observed defective migration in the in vitro assays, STAT4-deficient and WT neutrophils migrated equally well to the site of infection." (PMID 34138758, 2021). "After infection with the STAT4 lentiviral vector (LV-STAT4) in follicles of mice, the expression of STAT4 in ovaries of mice significantly increased, and the expression of KISS1 was significantly decreased." (PMID 40214477, 2025). "STAT4 is the transcription factor that is activated in response to IL-12 and IFNγ and stimulates Th1-mediated host protective responses during the infection." (PMID 38809023, 2024). "Nonetheless, they noted a moderate immune polarization on the Th1 side by the expression of IL-2, IL-12, IFN-γ, and transcriptional factors (STAT1 and STAT4) upon infection of dendritic cells with L. tarentolae expressing the SARS-CoV-2 full-length S." (PMID 39817166, 2024). "It is known that STAT3 plays a vital role in the production and continuation of memory cell populations and that STAT4 is majorly involved at the site of infection and in stimulating tissue-resident memory responses." (PMID 36916966, 2023). "It is also well-established that STAT3 and STAT4 play specific function in the formation of T cell memory subsets in response to infections." (PMID 36881595, 2023). "Further, STAT4 and Blimp1 transcription factors are known to regulate resident memory responses at the local site of infection." (PMID 36881595, 2023). "In this report, using STAT4–conditional mutant mice and bacterial infection in vivo, we define STAT4-dependent neutrophil functions during infection." (PMID 34138758, 2021). "Analysis of ex vivo isolated NK1.1+ cells from T. gondii-infected mice at 5 days post-infection revealed that signal transducer and activator of transcription 4 (STAT4) was phosphorylated, indicating activation of STAT4 by IL-12 in NK cells." (PMID 35053151, 2021). "Infection of Stat4–/– mice with Salmonella typhimurium, Klebsiella pneumonia, and Mycobacterium tuberculosis results in a bacterial burden that is orders of magnitude greater than controls." (PMID 34138758, 2021). "Although surprising, this agrees with recent reports showing a role for STAT4 in generating GC Tfh in infection." (PMID 32634740, 2020). "The STAT4 protein is turned on (activated) by immune system proteins called cytokines, which are part of the inflammatory response to fight infection." (PMID 30972105, 2019). "T cell transcription factors regulate specific immune response against pathogen after infection, hence we further studied the activation of different transcription factors STAT-4, STAT-6 after stimulation with M. leprae antigens." (PMID 30642265, 2019). "In contrast, our data suggest that IL-12, but not IL-2, is the key cytokine driving Th1 cell terminal differentiation during infection, presumably through STAT4 positive enforcement of T-bet expression." (PMID 23593003, 2013). "It is of interest that the main Th2 transcription factor STAT6 was upregulated during early infection, while a regulator of Th1 immunity, STAT4, was downregulated in the rabbit lungs at 4 weeks post-infection." (PMID 22645653, 2011). "Thus, we detected the activation of STAT1 and STAT4 at 8, 12, and 24 hours post-infection as possible downstream signaling of the induced pyroptosis." (PMID 39119293, 2024). "Whether the 018:STAT4 interaction plays a physiological role during infection remains to be determined." (PMID 35182467, 2022). "Weight loss through the course of the infection was not different between STAT4−/− and B6 control mice." (PMID 33446493, 2021).